KDM5B (lysine demethylase 5B)
Diseases named in the same sentence as KDM5B in open-access papers (continued):
Sharing a sentence is not in itself a finding about the gene and the disease.
autism spectrum disorder (4 papers, 2021 to 2023). A spectrum of developmental disorders that includes autism, and Asperger syndrome. "Based on the association between genetic variants in KDM5A, KDM5B, and KDM5C and ID and autism spectrum disorder (ASD), KDM5-interactors could potentially be implicated in neurological disorders." (PMID 36803422, 2023).
bladder tumors (4 papers, 2010 to 2023). "KDM5B inhibition increases immunogenicity in bladder tumor cells with FGFR3 mutation." (PMID 38004468, 2023). "KDM5B regulates the cell cycle of bladder tumor cells and an inverse relationship between KDM5B and connexin 26 is observed; KDM5B is overexpressed, while connexin 26 is underexpressed." (PMID 38004468, 2023). "Li and collaborators recently found an inverse relationship between Cx26 and JARID1B (also known as KDM5B) histone demethylase protein levels in transitional cancer cell lines and advanced human bladder tumors." (PMID 25018732, 2014). "The present study identified high expression of KDM5B, a JmjC histone demethylase, in the majority of bladder tumor tissues analyzed by real-time PCR." (PMID 20226085, 2010). "We previously reported the copy number gain at a region of chromosome 1q32.1 (200963156-201045186), where the KDM5B gene is located, in 17 of 98 bladder tumors (British cases)." (PMID 20226085, 2010). "In the present study, we demonstrated significantly higher expression of both E2F1 and E2F2 in bladder tumor tissues than in non-neoplastic tissues, which are probably due to aberrant transcriptional regulation of KDM5B." (PMID 20226085, 2010).
breast invasive carcinoma (4 papers, 2016 to 2025). "We found that STING expression level is lower in “KDM5B high” samples than in “KDM5B low” samples from multiple human tumor types, including breast invasive carcinoma, bladder urothelial carcinoma, and ovarian serous cystadenocarcinoma." (PMID 30080846, 2018). "Strikingly, in two hormone-driven cancers, breast and prostate cancers, we observed prevalent KDM5B genomic amplifications, which were accompanied by increased KDM5B mRNA expression in invasive breast cancer (BRCA), or increased or an increased trend of KDM5B mRNA levels in PCa." (PMID 33245716, 2020). "The KDM5B gene expression was elevated in most cancers compared to normal tissues, with significant overexpression observed in breast invasive carcinoma, pancreatic adenocarcinoma, and thymoma." (PMID 40764352, 2025).
COVID-19 (4 papers, 2021 to 2024). A disease caused by infection with severe acute respiratory syndrome coronavirus 2. "On the other hand, several genes with a positive correlation to ACE2 were found to be regulated by Lysine Demethylase 5B (KDM5B), a histone demethylase, highlighting the role of histone methylation in COVID-19 pathogenesis." (PMID 38400997, 2024). "Transcriptome analysis studies conducted from patients with hypertension and DM associated with severe COVID-19 cases revealed that ACE2 expression was potentially regulated synergistically by various histone marks such as histone acetyltransferase 1 (HAT1), HDAC2, and lysine demethylase 5B (KDM5B)." (PMID 34691068, 2021). "Importantly, the elevated ACE2 expression in the lungs of patients with severe COVID-19-related complications may be due to histone modifications of several genes such as HAT1, HDAC2, and lysine demethylase 5 B (KDM5B)." (PMID 34572329, 2021).
Ewing sarcoma (4 papers, 2022 to 2025). A small round cell tumor that lacks morphologic, immunohistochemical, and electron microscopic evidence of neuroectodermal differentiation. "In Ewing sarcoma, for instance, KDM5B attenuates FBXW7 transcription, leading to CCNE1 accumulation and enhanced proliferation." (PMID 40370434, 2025). "In conclusion, our study suggests that upregulation of KDM5B plays an important role in the process of cell proliferation in Ewing sarcoma." (PMID 35428764, 2022). "Our study further demonstrates the anti-tumor effect of KDM5B inhibitor AS-8351 in Ewing sarcoma." (PMID 35428764, 2022). "Therefore, targeting KDM5B could be a potential therapy to improve the treatment of Ewing sarcoma." (PMID 35428764, 2022). "KDM5B (JARID1B) inhibitor AS-8351 suppressed proliferation and induced cell cycle arrest in Ewing sarcoma cell lines." (PMID 36671446, 2022).
glioma (4 papers, 2018 to 2024). A benign or malignant brain and spinal cord tumor that arises from glial cells (astrocytes, oligodendrocytes, ependymal cells). "Collectively, this study demonstrates that the SNHG1- microRNA-154-5p/miR-376b-3p- FOXP2- KDM5B feedback loop plays a pivotal role in regulating the malignant behavior of glioma cells." (PMID 30728054, 2019). "KDM5B was highly expressed in the tissues and blood of glioma, and was positively correlated with the poor prognosis of patients." (PMID 30728054, 2019). "In order to further understand the role of KDM5B in glioma, U87 and U251 cells were transfected with KDM5B silencing plasmids, and the malignant biological behaviors of U87 and U251 cells were detected." (PMID 30728054, 2019). "This study proved that KDM5B was highly expressed in glioma tissues and cells, and increased with the pathological grade of glioma." (PMID 30728054, 2019). "The detection of downstream protein KDM5B was applied to the 7 groups of glioma cells transfected with miR-154-5p overexpression, miR-376b-3p overexpression, 3 ‘UTR wild-type and 3’ UTR mutant FOXP2 overexpression plasmid." (PMID 30728054, 2019). "Silencing the expression of KDM5B in cell experiments significantly reduced the expression of SNHG1 in glioma cells." (PMID 30728054, 2019). "Silencing the expression of KDM5B inhibits the proliferation, migration, and invasion of glioma cells and promotes apoptosis; the overexpression of KDM5B has the opposite effect." (PMID 30728054, 2019). "In this study, we intially identified the endogenous expression of SNHG1, miR-154-5p, miR-376b-3p, FOXP2, and KDM5B in gliomas." (PMID 30728054, 2019). "The results suggest that KDM5B acts as a tumor promoting gene in glioma tissues and cells." (PMID 30728054, 2019). "The results of this research further clarify the biological effects of KDM5B on glioma cells." (PMID 30728054, 2019). "The expression of KDM5B in glioma tissues was higher than that in normal brain tissues, while the expression of high grade pathological tissue was higher than that of low grade, and expression in glioma U87 and U251 cells was significantly higher than that in HA cells." (PMID 30728054, 2019). "KDM5B exerts the effect of RNA binding protein, acts on SNHG1 to form a positive feedback loop, and regulates the biological behavior of glioma cells." (PMID 30728054, 2019). "The results suggest that overexpression of miR-154-5p or miR-376b-3p can negatively regulate the expression of FOXP2, thereby affecting the transcription of target gene KDM5B by FOXP2, changing the expression of KDM5B, and inhibiting the malignant biological behavior of glioma cells." (PMID 30728054, 2019). "In summary, this study demonstrates that SNHG1 increases the expression of FOXP2 and KDM5B by regulating the expression of miR-154-5p and miR-376b-3p, and that KDM5B itself and its downstream PI3K/Akt pathway affect the biological behavior of glioma cells." (PMID 30728054, 2019).
head and neck squamous cell carcinoma (4 papers, 2016 to 2024). A squamous cell carcinoma that arises from any of the following anatomic sites: lip and oral cavity, nasal cavity, paranasal sinuses, pharynx, larynx, and salivary glands. "The prediction of TCGA link in the UALCAN database showed that KDM5B is highly expressed in head and neck squamous cell carcinoma." (PMID 39039611, 2024). "Bak protein was upregulated, whereas Bcl-2 was downregulated in the KDM5B-knockdown cells, indicating KDM5B maintained head and neck squamous cell carcinoma survival by regulating Bcl family members." (PMID 35333349, 2022). "KDM5B overexpression could also predict proliferation properties in head and neck squamous cell carcinoma and KDM5B knockdown resulted in G1 arrest and early apoptosis by suppressing Bcl-2 family members." (PMID 27974677, 2017).
liver cancer (4 papers, 2020 to 2024). An epithelial or non-epithelial malignant neoplasm that arises from the liver. "The histone demethylase KDM5B is highly expressed in several cancers including lung, stomach, breast and hepatic cancers, making it a potential therapeutic target for HCC." (PMID 33829656, 2021). "Peculiarly, HIF1α reportedly activates the expression of histone demethylase KDM5B in liver cancer cells." (PMID 33304897, 2020). "Furthermore, KDM5B is known to reduce the expression of PTEN by demethylating H3K4me3 in the promoter region of PTEN in liver cancer." (PMID 33304897, 2020).
lung adenocarcinoma (4 papers, 2015 to 2024). A carcinoma that arises from the lung and is characterized by the presence of malignant glandular epithelial cells. "It was found that KDM5B was highly expressed in lung adenocarcinoma." (PMID 33304897, 2020).
metastatic melanoma (4 papers, 2017 to 2023). A melanoma that has spread from its primary site to another anatomic site. "KDM5B is highly expressed in benign melanocytic nevi, whereas only a small fraction of tumor cells are KDM5B-positive in advanced and metastatic melanomas." (PMID 35805040, 2022).
multiple myeloma (4 papers, 2016 to 2019). "By employing a KDM5 enzymes inhibitor in myeloma cells, a higher quartile of KDM5B expression was found to be associated with shorter overall survival in myeloma patients." (PMID 31548641, 2019). "Compound 59c also showed an inverse relationship between KDM5B expression and overall survival from three clinical multiple myeloma trials’ data, suggesting a potential application for KDM5B inhibitors in myeloma therapy." (PMID 29651880, 2018). "For example, here we reported that KDOAM-25 shows an inverse relationship between KDM5B expression and overall survival using data from three clinical multiple myeloma trials, thus suggesting a potential application for KDM5B inhibitors in myeloma therapy." (PMID 28262558, 2017). "KDM5B is overexpressed in multiple myeloma and negatively correlated with the overall survival." (PMID 28262558, 2017).
prostate (4 papers, 2013 to 2023). "Collectively this data suggests KDM5B is necessary for PCa cell viability and contributes to prostate carcinogenesis." (PMID 37152294, 2023). "Additionally, KDM5B protein stability was regulated by S-phase kinase associated protein-2 (SKP2), which elevated H3K4me3 level to facilitate prostate carcinogenesis by promoting ubiquitination-dependent degradation of KDM5B." (PMID 27974677, 2017).
schizophrenia (4 papers, 2017 to 2024). A major psychotic disorder characterized by abnormalities in the perception or expression of reality. "Six candidate genes (SFN, KDM5B, MYLK, IRF3, IRF7, and ID1) were identified with diagnostic significance for schizophrenia." (PMID 37113536, 2023). "Furthermore, we established a schizophrenia diagnostic model based on genes associated with cellular senescence, which contain 6 candidate genes (SFN, KDM5B, MYLK, IRF3, IRF7, ID1)." (PMID 37113536, 2023). "PHF8, SAP30 and KDM5B as co regulators of the three hub genes may provide a new idea for the treatment of schizophrenia." (PMID 36421842, 2022).
atherosclerosis (3 papers, 2022 to 2025). A disease characterized by the build-up of fatty material and calcium deposition in the arterial wall resulting in partial or complete occlusion of the arterial lumen. "RNA sequencing on shKdm5b HUVECs implied that KDM5B is associated with endothelial inflammation and atherosclerosis." (PMID 39643939, 2024). "In this study, we examined the endothelial expression of the demethylase KDM5B upon flow disturbance and its role in the development of atherosclerosis." (PMID 39643939, 2024). "The mechanosensor Piezo1 and the downstream transcription factors c‐JUN and ETS1 regulate KDM5B expression, and KDM5B potentially contributed to atherosclerosis by regulating endothelial inflammation." (PMID 39643939, 2024). "We thus investigated the mechanisms regulating endothelial KDM5B expression under d‐flow conditions and explored the potential contribution of vascular KDM5B to atherosclerosis progression in mice." (PMID 39643939, 2024). "We found that disturbed flow, a pro-atherogenic force, upregulates the expression of the histone demethylase KDM5B via the Piezo1-ETS-1/c-JUN pathway and that KDM5B then downregulates H3K4me3 at anti-inflammatory gene promoters, exacerbating endothelial inflammation and atherosclerosis." (PMID 41403695, 2025). "KEGG signalling pathway analysis of the differentially expressed genes revealed enrichment of the ‘lipid and atherosclerosis’, ‘fluid sehear stress and atherosclerosis’, and ‘NF‐κB signaling pathway’, suggesting the involvement of endothelial KDM5B in the development of atherosclerosis." (PMID 39643939, 2024). "Our findings indicate that endothelial KDM5B expression induced by d‐flow via the Piezo1 pathway promotes atherosclerotic plaque formation, providing targets for the prevention or therapeutic intervention of atherosclerosis." (PMID 39643939, 2024). "We showed that endothelial KDM5B expression induced by d‐flow was regulated by Piezo1 and KDM5B may contributes to atherosclerosis potentially by regulating endothelial cell inflammation." (PMID 39643939, 2024). "However, whether disturbed flow controls KDM5B‐mediated histone demethylation and its subsequent potential to modulate endothelial gene expression and contribute to the development of atherosclerosis remain unknown." (PMID 39643939, 2024). "Additionally, endothelial KDM5B deficiency did not affect body weight during the development of atherosclerosis." (PMID 39643939, 2024).
endometrial carcinoma (3 papers, 2022 to 2024). A malignant tumor arising from the epithelium that lines the cavity of the uterine body. "Regulation of KDM5B by miR-29c was described in endometrial carcinoma, showing a correlation between elevated levels of KDM5B and tumor grade and paclitaxel resistance." (PMID 39311383, 2024). "KDM5B knockdown enhances the chemosensitivity of endometrial cancer cells towards paclitaxel." (PMID 38842683, 2024).
gastric tumour (3 papers, 2021 to 2024). "Furthermore, higher levels of KDM5B in stomach tumour tissues were significantly associated with a poor prognosis (P = 0.020)." (PMID 38862740, 2024). "Moreover, KDM5B is associated with metastasis development through the Akt pathway, and Akt inhibitors reduce gastric tumor cell migration." (PMID 38004468, 2023). "IHC analysis of gastric tumours and adjacent normal tissues further proved that KDM5B levels in CAFs were significantly higher than those in NFs." (PMID 38862740, 2024). "Collectively, these results indicate that binding of KDM5B to pRB1 limits the transcriptional regulation of IL-8 expression in gastric tumour cells." (PMID 38862740, 2024). "Immunofluorescence assays with gastric tumour tissues also showed that KDM5B was mainly expressed in most of CAFs." (PMID 38862740, 2024). "Next, we investigated the underlying mechanisms for the difference of IL-8 production between gastric tumour cells and CAFs, although both expressed KDM5B." (PMID 38862740, 2024). "KDM5B is overexpressed in gastric tumors, being related to tumor proliferation, migration, and invasion, with reduced immune cell infiltration within the tumor, and it is associated with poor prognostic outcomes, functioning as a tumor promoter." (PMID 38004468, 2023). "Overexpression of KDM5B can also increase invasion in vitro and metastatic potential of gastric tumours in vivo, by activating the Akt pathway." (PMID 34493070, 2021). "Co-IP experiments showed that KDM5B could bind to pRB1 in gastric tumour cells." (PMID 38862740, 2024). "Therefore, we speculated that the failure to produce IL-8 in gastric tumour cells may be attributed to the competitive binding of the KDM5B transcription site by pRB1." (PMID 38862740, 2024).
glioblastoma (3 papers, 2017 to 2024). The most malignant astrocytic tumor (WHO grade IV). "Strikingly, KDM5B was also identified by Patel and co-workers to be significantly higher expressed in non-cycling glioblastoma cells." (PMID 27903987, 2017).
oral squamous cell carcinoma (3 papers, 2018 to 2023). "The promoting effects of KDM5B on radiation sensitivity have been validated in oral squamous cell carcinoma." (PMID 35333349, 2022). "Untreated oral squamous cell carcinoma (OSCC) cells contain CSC‐like cells, which exhibit KDM5B upregulation, suggesting that DTCs might have presented in the original OSCC cell bank." (PMID 37638338, 2023).
osteosarcoma (3 papers, 2021 to 2023). A usually aggressive malignant bone-forming mesenchymal neoplasm, predominantly affecting adolescents and young adults. "Vitamin C can coactivate KDM5B/C to demethylate H3K4me3, and KDM5B (JARID1B) has been shown to increase DNA DSB repair by recruiting factors Ku70 and BRCA1 in osteosarcoma (U2OS) cells." (PMID 34017357, 2021). "Moreover, in osteosarcoma (U2OS) cells, vitamin C increased the ability of KDM5B/C to demethylate H3K4me3, and KDM5B has been shown to increase DNA double-strand break repair by recruiting factors Ku70 and BRCA1." (PMID 36979633, 2023).
viral infection (3 papers, 2020 to 2023). "KDM5B interacted with HDAC1 to downregulate TLR9 expression by modulating its promoter activity, thus suppressing viral infection." (PMID 37353521, 2023).
Arrhythmia (2 papers, 2024). Any cardiac rhythm other than the normal sinus rhythm. "Eight of these associations were novel (LMNA, SMAD6, HSPB9, TMEM95, KLF1, TET2, NME3, KDM5B) and 5 genes have previously been linked to arrhythmias (SCN5A, TTN, RPL3L, PKP2, PMVK)." (PMID 38390584, 2024).
diabetes (2 papers, 2019 to 2022). "In this study, we wished to investigate the effect of lysine demethylase inhibition in vivo on experimental diabetes and elucidate the specific role of KDM5B on insulin secretion." (PMID 31467927, 2019). "High expression of KDM5B was significantly correlated with age ≤65 years old (p = 0.036), no history of diabetes (p = 0.038), higher tumor grade (p = 0.048), more advanced clinical stage (p = 0.004), and more advanced T stage (p = 0.020)." (PMID 35493099, 2022).
epilepsy (2 papers, 2023 to 2024). A brain disorder characterized by episodes of abnormally increased neuronal discharge resulting in transient episodes of sensory or motor neurological dysfunction, or psychic dysfunction. "This study also reported an association of protein-truncating variants of KDM5B with neurodevelopmental and psychiatric disorders and epilepsy." (PMID 38575342, 2024). "We identified 35 KDM5B PTV carriers who had been diagnosed with psychiatric disorders, epilepsy or Parkinson disease based on hospital diagnostic codes (enriched for disease cases compared with EUR non-KDM5B PTV carriers; P = 0.0005)." (PMID 37231097, 2023).
fibrosis (2 papers, 2022 to 2023). the formation of excess fibrous connective tissue in an organ or tissue in a reparative or reactive process. "Our study indicates that KDM5B drives pathological cardiac fibrosis and represents a candidate target for intervention in cardiac dysfunction and heart failure." (PMID 36481938, 2022). "Finally, the authors preventedthe fibroblast transition into myofibroblast by inhibiting KDM5B invitro and in vivo, thus proposing KDM5B as possible candidate target toameliorate cardiac fibrosis and remodelling." (PMID 39076707, 2023).